SAR1B (secretion associated Ras related GTPase 1B)
Description:
Small GTPase that cycles between an active GTP-bound and an inactive GDP-bound state and mainly functions in vesicle-mediated endoplasmic reticulum (ER) to Golgi transport. The active GTP-bound form inserts into the endoplasmic reticulum membrane where it recruits the remainder of the coat protein complex II/COPII. The coat protein complex II assembling and polymerizing on endoplasmic reticulum membrane is responsible for both the sorting of cargos and the deformation and budding of membranes into vesicles destined to the Golgi. In contrast to SAR1A, SAR1B specifically interacts with the cargo receptor SURF4 to mediate the transport of lipid-carrying lipoproteins including APOB and APOA1 from the endoplasmic reticulum to the Golgi and thereby, indirectly regulates lipid homeostasis. In addition to its role in vesicle trafficking, can also function as a leucine sensor regulating TORC1 signaling and more indirectly cellular metabolism, growth and survival. In absence of leucine, interacts with the GATOR2 complex via MIOS and inhibits TORC1 signaling. The binding of leucine abrogates the interaction with GATOR2 and the inhibition of the TORC1 signaling. This function is completely independent of the GTPase activity of SAR1B.
Synonyms: GTBPB; SARA2; ANDD; CMRD
Tractability: Small molecule: a structure with a bound ligand is known. Antibody: UniProt places it where antibodies can reach, with medium confidence. PROTAC: ubiquitination databases record sites on it; its protein half-life has been measured.
Gene: Protein-coding gene on chromosome 5 (134,601,149 to 134,649,271, reverse strand). Ensembl gene ENSG00000152700.
Subcellular location: Endoplasmic reticulum membrane; Golgi apparatus, Golgi stack membrane; Cytoplasm, cytosol; Lysosome membrane
Subcellular location (Human Protein Atlas): Endoplasmic reticulum
Pathways (Reactome):
Immune System: Antigen Presentation: Folding, assembly and peptide loading of class I MHC; MHC class II antigen presentation
Vesicle-mediated transport: COPII-mediated vesicle transport; Cargo concentration in the ER
Disease: SARS-CoV-2 activates/modulates innate and adaptive immune responses
Metabolism: Regulation of cholesterol biosynthesis by SREBP (SREBF)
Transport of small molecules: Chylomicron assembly
Gene Ontology:
Molecular function: amino acid sensor activity; G protein activity; GTPase activity; protein binding; GTP binding
Biological process: cellular response to leucine starvation; COPII vesicle coating; COPII-coated vesicle cargo loading; endoplasmic reticulum to Golgi vesicle-mediated transport; lipid homeostasis; lipoprotein transport; negative regulation of TORC1 signaling; regulation of lipid transport; regulation of TORC1 signaling; antigen processing and presentation of peptide antigen via MHC class I; membrane organization; positive regulation of ER to Golgi vesicle-mediated transport; vesicle organization; intracellular protein transport; lipid export from cell
Cellular component: COPII vesicle coat; cytosol; endoplasmic reticulum exit site; endoplasmic reticulum membrane; lysosomal membrane; endoplasmic reticulum; ER to Golgi transport vesicle membrane; Golgi cisterna membrane
Genetic constraint (gnomAD): Loss-of-function variants: 14 observed, 19.81 expected, observed/expected ratio (o/e) 0.71, 90% interval 0.47 to 1.11. The upper end of that interval is the gene's LOEUF score, 1.11, which puts it in group 4 of 6, group 1 being the genes least tolerant of losing a copy. Missense variants: 144 observed, 197.17 expected, observed/expected ratio (o/e) 0.73, 90% interval 0.64 to 0.84. Synonymous variants: 53 observed, 71.05 expected, observed/expected ratio (o/e) 0.75, 90% interval 0.6 to 0.94.
Homologues: Orthologues: chimpanzee SAR1B (99% identical), dog SAR1B (99% identical), mouse Sar1b (99% identical), pig SAR1B (99% identical), rat Sar1b (99% identical), guinea pig SAR1B (98% identical), macaque SAR1B (91% identical), rabbit SAR1B (86% identical), tropical clawed frog sar1b (84% identical). Paralogues in human: SAR1A (90% identical), ARF1 (31% identical), ARL14 (31% identical), ARF3 (31% identical), ARF4 (31% identical), ARF5 (31% identical), TRIM23 (31% identical), ARF6 (30% identical), ARL4D (30% identical), ARL4A (30% identical), ARL5B (30% identical), ARL1 (29% identical), and 18 more.
Diseases named in the same sentence as SAR1B in open-access papers:
SAR1B is named in the same sentence as 34 diseases in open-access papers, as found by Europe PMC text mining. Sharing a sentence is not in itself a finding about the gene and the disease. The quoted sentences say what the papers report.
chylomicron retention disease (27 papers, 2011 to 2026). Chylomicron retention disease (CRD) is a type of familial hypocholesterolemia characterized by malnutrition, failure to thrive, growth failure, vitamin E deficiency and hepatic, neurologic and ophthalmologic complications. "Chylomicron retention disease is a life-threatening disease caused by a rare autosomal mutation in the SAR1B gene, and patients cannot absorb fats or fat-soluble vitamins due to the lack of chylomicron synthesis and secretion." (PMID 41516090, 2025). "SAR1B deficiency in humans results in a unique lipid disorder termed Anderson disease or chylomicron retention disease (CMRD)." (PMID 39545422, 2024). "Sar1B Mutations in SAR1B were identified in a number of families with chylomicron retention disease (OMIM: 246700)." (PMID 38314136, 2024). "Biallelic pathogenic variants of the Sar1b gene cause chylomicron retention disease (CRD) whose central phenotype is the inability to secrete chylomicrons." (PMID 37558128, 2023). "Chylomicron retention disease, or Anderson’s disease, is a rare autosomal recessive disorder caused by biallelic loss-of-function alterations in the SAR1B gene that leads to failure of chylomicron secretion from enterocytes." (PMID 37138899, 2022). "For example, loss of SAR1B leads to chylomicron retention disease/Anderson's disease, which results in inability to transport newly synthesized chylomicrons out of intestinal epithelial cells (7, –, 12)." (PMID 32358066, 2020). "Both SAR1 paralogs are highly expressed in the intestine, and SAR1A expression increases in chylomicron retention disease/Anderson's disease patients, but this increase is insufficient to compensate for loss of SAR1B." (PMID 32358066, 2020). "In humans, several distinct mutations affecting one of the Sar1 isoforms (SAR1B) have been implicated in chylomicron retention disease (Anderson disease), an early onset, inherited lipid malabsorption disorder characterized by hypocholesterolemia." (PMID 26546679, 2016). "Mutations in human SAR1B result in chylomicron retention disease (Anderson Disease), a distinct defect in fat absorption due to reduced chylomicron assembly and secretion by intestinal enterocytes." (PMID 23580231, 2013). "Chylomicron retention disease is a rare disease caused by biallelic pathogenic variants in the SAR1B gene, leading to a defect in chylomicron secretion by the intestinal tract and ultimately to a defect in lipid absorption and chylomicron retention in the intestine." (PMID 39199213, 2024). "For example, increasing the expression of SEC23A could be considered to treat congenital CDAII (due to deficiency of SEC23B), or SAR1A to treat Anderson disease (due to deficiency of SAR1B)." (PMID 39545422, 2024). "Chylomicron retention disease (Anderson disease) is a result for variant of the SAR1B gene." (PMID 34629076, 2021). "Chylomicron retention disease (CMRD) is a rare autosomal recessive disorder caused by pathogenic variants of SAR1B, in which defective intestinal chylomicron secretion leads to fat malabsorption, hypocholesterolemia, and failure to thrive in infancy." (PMID 41767779, 2026). "A third congenital disorder, called chylomicron retention disease (CRD), has been identified subsequently, and is caused by mutations in the Sar1b gene, coding for a GTPase protein of the Ras superfamily." (PMID 37558128, 2023). "Mutations of the SAR1B gene, which encodes for the Sar1b protein, are mapped to chromosome 5q31.1 and are implicated in the development of chylomicron retention disease (CRD), now presumed to be the same disorder as Anderson disease." (PMID 36422736, 2023). "Chylomicron retention disease (CRD) is an autosomal recessive disorder associated with biallelic Sar1b mutations leading to defects in intracellular chylomicron (CM) trafficking and secretion." (PMID 33964306, 2021). "Mutations in SAR1B cause chylomicron retention disease (CMRD), characterized by enterocyte failure to secrete large lipoprotein particles." (PMID 34169326, 2021).
chylomicron retention disease (continued). "Patients with mutations in SAR1B have Chylomicron retention disease (CMRD), a hypocholesterolemic disorder characterized by lipid malabsorption." (PMID 30336591, 2018). "Abetalipoproteinemia (FHBL-SD1) and chylomicron retention disease (FHBL-SD3) are rare recessive disorders of lipoprotein metabolism due to mutations in MTTP and SAR1B genes, respectively, which lead to defective chylomicron formation and secretion." (PMID 36771214, 2023). "Chylomicron retention disease (CMRD), also known as Anderson's disease, is an autosomal recessive condition with a genetic mutation in the secretion associated Ras related GTPase 1B (SAR1B) gene, a protein coding gene." (PMID 32257723, 2020). "Although chylomicron retention disease or Anderson's disease has been shown to be attributable to variations in the SAR1B gene, a full understanding of the relationship between genotype and phenotype and the origins of tissue-specific manifestations is lacking." (PMID 21235735, 2011). "Finally, for the first time, we describe the differential expression of the SAR1A and SAR1B genes and the localization of the Sar1 proteins in the enterocytes of intestinal biopsies from Anderson's disease patients as compared to healthy individuals." (PMID 21235735, 2011). "Chylomicron Retention Disease (CMRD) (OMIM#246700), also called Anderson’s Disease (OMIM#607689), is a rare genetic disease due to mutations in the SARA2 gene coding for the Sar1b GTPase protein." (PMID 27520363, 2016). "Chylomicron retention disease (CMRD), Anderson disease, and CMRD with the neuromuscular disorder Marinesco-Sjogren syndrome (MSS) are all inherited disorders of severe fat malabsorption with impaired chylomicron transport and found to be associated with mutations in Sar1B." (PMID 26082182, 2015). "Sar1B, a coat protein II (COPII) component, has also been shown to be central to the lipid economy by the discovery that its mutations cause the rare recessive disorder chylomicron retention disease (CMRD) (OMIM 246700)." (PMID 24338480, 2014). "Notably, germline mutations in human SAR1B, one of the two SAR1 paralogs, cause chylomicron retention disease (CMRD), an inborn metabolic defect in fat absorption due to the retention of chylomicrons (the APOB-containing lipoprotein produced in the gut) in the small intestine." (PMID 38216994, 2024). "Although both SAR1 paralogs are highly expressed in the intestine, only mutations in SAR1B have been linked to the rare autosomal recessive disorder chylomicron retention disease (CMRD, or Anderson’s disease), and no human disorder has yet been associated with mutations in SAR1A." (PMID 36594468, 2023).
Hypocholesterolemia (6 papers, 2014 to 2026). An decreased concentration of cholesterol in the blood. "Chylomicron and VLDL synthesis are both severely compromised in two recessive disorders causing severe hypocholesterolemia: chylomicron retention disease, which is caused by Sar1b deficiency, and abetaliproteinemia, which is due to deficiency of MTTP." (PMID 27013658, 2016). "For the cases with hypocholesterolemia phenotype, we studied five genes (APOB, PCSK9, MTTP, SAR1B, and ANGPTL3)." (PMID 37138899, 2022).
abetalipoproteinemia (4 papers, 2014 to 2023). "Thus, loss of Sar1B's lipoprotein secretion-promoting activity appears to impair apoB lipoprotein production, albeit to a lesser extent than the impairment that occurs in abetalipoproteinemia." (PMID 24338480, 2014). "Indeed, mutations in microsomal triglyceride transfer protein (MTP) or in secretion-associated Ras related GTPase 1B (SAR1B), lead to abetalipoproteinemia and chylomicron retention diseases, respectively." (PMID 29165370, 2017). "But regardless of the etiopathogenesis, homozygous mouse models of hypobetalipoproteinemia, abetalipoproteinemia, and CRD share embryonic lethality, which emphasizes the critical importance of their respective proteins Apo B, MTTP, and Sar1b." (PMID 33964306, 2021).
colorectal cancer (3 papers, 2020 to 2022). A primary or metastatic malignant neoplasm that affects the colon or rectum. "It has also been proved that removal of SAR1B inhibited the proliferation and induced apoptosis of colorectal cancer cells." (PMID 34465365, 2021). "Finally, SAR1B was identified as a potential metastatic suppressor in colorectal cancer, through a targeted proteomic approach." (PMID 32426352, 2020). "Also, migration and invasion assays showed that SAR1B silencing leads to an increase in colorectal cancer cell motility and invasive capacity." (PMID 32426352, 2020). "After the knockdown of NbSar1, we found that the proliferation of N. bombycis was significantly inhibited, which is consistent with previous research showing that the knockdown of Sar1B suppressed cell proliferation and induced significant apoptosis of RKO (colorectal cancer) cells." (PMID 36301095, 2022).
fatty liver (3 papers, 2014 to 2023). "Moreover, Sar1b +/+ mice showed phenotypes of dyslipidemia, obesity, and liver steatosis and were susceptible to IR." (PMID 36817150, 2023). "Our findings may indicate a novel link between Sar1b-mediated lipid absorption and metabolism, which is supported by our previous work pointing out that transgenic mice overexpressing Sar1b developed a rise in body weight, adiposity, hepatic steatosis, plasma lipids and insulin insensitivity." (PMID 37558128, 2023). "Because clinical studies have indicated that SAR1B mutations affect chylomicron secretion and, despite intestinal fat malabsorption, some children with CMRD develop fatty liver (2, 16, –, 18), we examined relative SAR1A and SAR1B mRNA levels in human intestinal biopsies and liver samples." (PMID 24338480, 2014). "We provide strong evidence that Sar1B promotes the secretion of triglyceride-rich, apoB-containing lipoproteins from the liver, which would neatly explain the counter-intuitive observation that some CMRD children develop hepatic steatosis, despite severe intestinal fat malabsorption (16, –, 18)." (PMID 24338480, 2014).
hepatoma (2 papers, 2020 to 2022). "In this study, we investigated the effects of Sar1a and Sar1b on numbers, size, and components of LDs in the human hepatoma cell line HuH7 cells." (PMID 35742827, 2022). "For this purpose, we developed CRISPR-Cas9–mediated SAR1B knockdown with the lipoprotein-secreting rat hepatoma cell line McArdle RH7777." (PMID 32358066, 2020).
Hypercholesterolemia (2 papers, 2021 to 2024). An increased concentration of cholesterol in the blood.
Marinesco-Sjogren syndrome (2 papers, 2011 to 2015). Marinesco-Sjogren syndrome (MSS) belongs to the group of autosomal recessive cerebellar ataxias. "In the cases of CMRD-MSS (Marinesco-Sjogren Syndrome), there is, in addition to a mutation in the SAR1B gene, a mutation in the SIL1 gene." (PMID 21235735, 2011).
Obesity (2 papers, 2023 to 2024). Accumulation of substantial excess body fat. "In humans, Plscr3 and Sar1b are linked to obesity and lipid metabolic disease, respectively, Kif21a is linked to ocular disease, and Nlgn2 is linked to schizophrenia (MGI)." (PMID 38968323, 2024).
Andersen disease (1 paper, 2017). "Of interest, mutations in the Sar1B nucleotide binding regions lead to genetic diseases such as the chylomicron retention disease, and Andersen disease, characterized by defects in transport of large chylomicrons, suggesting that Sar1B is required for large cargo secretion." (PMID 28879181, 2017).
endometrial cancer (1 paper, 2022). Primary or metastatic malignant neoplasm involving the endometrium (mucous membrane that lines the endometrial cavity). "In the case of the ADP-ribosylation factor (ARF)/ARF-like protein (ARL) family, it was observed that a high expression of ARL4D, ARL1, ARF1, and SAR1B in endometrial cancer is associated with better prognosis, while a high expression of ARL4C, ARL2, ARL10, ARL16, and ARL14 promotes worse survival." (PMID 35163161, 2022).
steatosis (1 paper, 2021). Increased lipid within the cytoplasm of cells. "However, unexpectedly, only sporadic and very limited steatosis was noticed in few patients with CRD despite Sar1b aberrations." (PMID 33964306, 2021).
infection (2 papers, 2022 to 2025). The state of being infected such as from the introduction of a foreign agent such as serum, vaccine, antigenic substance or organism. "(g and h) Quantification of typhoid toxin export into the infection medium of parental HEK293T and Sar1B-deficient cells after infection with S. Typhi." (PMID 35579416, 2022).
tumor (2 papers, 2018 to 2019). "Apart from SAR1B, ZBTB33, STYX, KLRC3, and S100Z, there were significant differences in the other 10 DEGs levels in the tumor-stroma crosstalk." (PMID 30519576, 2018).
SAR1B also shares sentences with these, for which no sentence is quoted: cancer (3 papers); Failure to thrive (2); genetic disease (2); hypobetalipoproteinemia (2); Alagille syndrome (1); atherosclerosis (1); breast carcinoma (1); cataract (1); colorectal tumor (1); congenital dyserythropoietic anemia (1); congenital dyserythropoietic anemia type 2 (1); craniolenticulosutural dysplasia (1); cystinosis (1); dyslipidemia (1); Hypofibrinogenemia (1); liver cirrhosis (1); Mitosis (1); osteogenesis imperfecta (1); schizophrenia (1); Wilson disease (1).